CDK6 (cyclin dependent kinase 6)
Diseases named in the same sentence as CDK6 in open-access papers (continued):
Sharing a sentence is not in itself a finding about the gene and the disease.
head and neck squamous cell carcinoma (7 papers, 2015 to 2021). A squamous cell carcinoma that arises from any of the following anatomic sites: lip and oral cavity, nasal cavity, paranasal sinuses, pharynx, larynx, and salivary glands. "Enhanced levels of CDK6 have been detected in patients with squamous-cell esophageal carcinoma and head and neck squamous cell carcinoma with high nuclear CDK6 expression tending to have advanced tumor status." (PMID 29464035, 2018). "Cdk6 is highly expressed in head and neck squamous cell carcinoma and significantly correlates with tumor progression." (PMID 26822763, 2016). "CDK6 alterations occur in 26 cancer types, mostly in esophageal squamous cell carcinoma (95, 12.63%), esophagogastric adenocarcinoma (514 cases, 9.14%), and head and neck squamous cell carcinoma (523 cases, 4.78%)." (PMID 33668805, 2021). "For instance, palbociclib and abemaciclib, which are inhibitors of the cell cycle-related kinases CDK4 and CDK6, show an anti-tumor effect in a patient-derived xenograft (PDX) model of head and neck squamous cell carcinoma (HNSCC)." (PMID 32610557, 2020). "Further investigation of the molecular mechanism demonstrated that NEAT1 sponges miR-107 to upregulate the expression of cyclin-dependent kinase 6 (CDK6), a member of the CDK family that significantly correlates with head and neck squamous cell carcinoma progression." (PMID 34512157, 2021). "Furthermore, CDK6 was negatively correlated with tumor purity in BRCA (r = −0.31833, p = 7.21 × 10−25), head and neck squamous cell carcinomas (HNSCs) (r = −0.06379, p = 0.157308), LIHC (r = −0.11342, p = 0.034946), and LUADs (r = −0.16182, p = 0.000304)." (PMID 33668805, 2021).
microcephaly (7 papers, 2015 to 2025). A congenital or acquired developmental disorder in which the circumference of the head is smaller than normal for the person's age and sex. "We used coding variation, transcript and protein levels, to uncover 12 genes likely mediating the effect of these variants, including GLI3 and CDK6 that affect cranial synostosis and microcephaly, respectively." (PMID 36415660, 2022). "The opposite phenotypes produced by CDK6 loss-of-function and cyclin D2 gain-of-function mutations (microcephaly vs megalencephaly, respectively) are remarkably predictable considering that the two proteins heterodimerize to produce an active protein kinase." (PMID 32762766, 2020). "Controls cell cycle/organises microtubules, CDK6 mutation affects apical neuronal precursor cells proliferation/reduces progenitor pool/decreases neuronal production/primary microcephaly." (PMID 25951892, 2015). "Also, the homozygous Ala197Thr missense mutation does not affect CDK6 protein stability, and an alternative pathogenic role for CDK6 in centrosome and microtubule organization was proposed as causal for microcephaly." (PMID 40210435, 2025). "With CDK6 primary microcephaly previously reported, discovering CDK4 mutations as a cause for microcephaly seems on the face of it unsurprising." (PMID 40210435, 2025). "Moreover, 4 of the 168 CDK6 interactors listed in the Biogrid database are involved in human disorders that include microcephaly." (PMID 32762766, 2020). "Many genes have been implicated in the development of microcephaly (summarized inTable 1) includingASPM,MCPH1,CDK5RAP2,CEP152,CENPJ,WDR62,STIL,CASC5,CEP135,ZNF335,PHC1,CDK6, with many of them contributing to centrosome and spindle protein dysfunction during mitosis." (PMID 26535115, 2015). "Therefore, extreme microcephaly observed in both CDK6 and CDK4 cases do not share a common mechanism." (PMID 40210435, 2025). "Notably, such short stature does not occur in CDK6 primary microcephaly." (PMID 40210435, 2025).
Obesity (7 papers, 2014 to 2025). Accumulation of substantial excess body fat. "Likewise, CDK4 and CDK6 have been implicated in metabolic disorders, including diabetes and obesity." (PMID 41388212, 2025). "Hypothesizing that changes in the placenta upon n-3 LCPUFA intervention during pregnancy are involved in the programming of offspring obesity risk, we discovered that placental CDK6 and PCNA mRNA levels were positively correlated with offspring birth weight and birth weight percentiles." (PMID 25348288, 2014). "Together with our previous findings that mice carrying a kinase inactive CDK6 mutant allele (K43M) had a reduced fat deposition and leaner body mass, these results demonstrate that CDK6 kinase activity induces obesity." (PMID 37664186, 2023). "To understand the functional relevance of CDK6 in obesity and its related diabetes, we utilized CDK6 knockout and knockin mice." (PMID 29523786, 2018). "Thus, pharmacological stimulation of DNL in WAT by CDK6 inhibitors is an intriguing possibility for the treatment of diabetes and obesity-related metabolic disorders." (PMID 38316780, 2024). "However, the molecular roles that CDK6 and RUNX1 play in obesity and its associated metabolic diseases remains largely unexplored." (PMID 29523786, 2018). "Therefore, targeting CDK6 may be a therapeutic strategy to treat obesity and its related metabolic diseases." (PMID 29523786, 2018). "In addition, CDK6 inhibited the white-to-beige fat transition by suppressing the transcription marker RUNX1, making it a promising therapeutic target for obesity and related metabolic disorders." (PMID 41388212, 2025). "Specifically, mouse models lacking CDK6 present improved energy expenditure, glucose tolerance and insulin sensitivity, as well as enhanced resistance to high-fat diet-induced obesity." (PMID 41388212, 2025). "Notably, a marked increase in lipogenesis and lipid accumulation was observed in the WAT of mouse models with impaired CDK6 activity, further corroborating the potential of CDK4/6 inhibition as a therapeutic strategy for obesity-related metabolic disorders." (PMID 41388212, 2025). "Finally, miR-107 was found to inhibit cyclin-dependent kinase 6 (CDK6) expression in adipocytes, which regulates adipogenesis and lipid storage, which leads to obesity and dyslipidemia." (PMID 35454146, 2022). "Here, authors found that inhibition of cyclin-dependent kinase 6 increased de novo lipogenesis in the adipose tissues but not in the liver, which may provide a strategy to concur obesity-induced maladies." (PMID 38316780, 2024). "Our findings indicate that CDK6 kinase activity negatively regulates the conversion of fat-storing cells into fat-burning cells by suppressing RUNX1, and suggest that CDK6 may be a therapeutic target for the treatment of obesity and related metabolic diseases." (PMID 29523786, 2018). "We demonstrate that mice lacking the CDK6 protein or its kinase domain (K43M) exhibit significant increases beige cell formation, enhanced energy expenditure, better glucose tolerance, and improved insulin sensitivity, and are more resistant to high-fat diet-induced obesity." (PMID 29523786, 2018). "In the absence of CDK6 protein/kinase activity, RUNX1 is stabilized, BAT-specific protein expression is increased, and obesity and its related metabolic diseases are suppressed." (PMID 29523786, 2018).
thyroid cancer (7 papers, 2014 to 2024). "It has also been known to fuction as a tumour supressor through regulation of CDK6 in thyroid cancer." (PMID 24626163, 2014). "MiR-298 could target the expression of CDK6 to inhibit the proliferation of thyroid cells and promote the apoptosis of thyroid cancer cells." (PMID 38978074, 2024).
viral infection (7 papers, 2016 to 2022). "In support of our notion, mass spectrometry analysis revealed that S130 in p21 is indeed phosphorylated in mitotic HeLa cells, although this residue is also phosphorylated by Cdk2/cyclin E in the S phase, Cdk6/cyclin K upon viral infection and ERK2 after mitogenic stimuli." (PMID 27384476, 2016). "Consistent with this common role across distinct viral infections, we observed robust intersection between the CDK family HCTs (q-values: SARS1, 8e-23; SARS2, 2e-31; MERS, 1e-30) and the CDK6 HCTs (q-values: SARS1, 1e-7; SARS2, 8e-8; MERS, 3e-4) and those of all viral HCTs." (PMID 32511379, 2020). "Although viral infection also resulted in cyclin D1, CDK4, and CDK6 down-regulation on protein level, the level of down-regulation is not as robust as that of cyclin D3, and their protein levels could not be rescued by protease and calpain inhibitor when compared with cyclin D3." (PMID 28130444, 2017).
astrocytoma (6 papers, 2011 to 2025). "In this study, miR-137 was found to be a direct inhibitor of CDK6, suggesting a role of this miRNA in astrocytoma cell proliferation." (PMID 21373187, 2011). "Others have reported that faster progressing mutant IDH1-driven astrocytomas had increased copy numbers in EGFR, MYC, MET, and CDK6 compared to slower-progressing patients." (PMID 40188944, 2025). "Alterations of CDK6, CDKN2A, CDKN2B, FGFR2, and MYC were more likely to be detected in WHO grade 4 astrocytoma, while variations of chromosome 19q had a higher frequency in WHO grade 2–3 astrocytoma." (PMID 38970209, 2024). "IDH‐mutant astrocytoma grade 4 group exhibited a higher frequency of alternations in FGFR2, CDK6, and MYC." (PMID 38970209, 2024).
meningioma (6 papers, 2012 to 2024). A generally slow growing tumor attached to the dura mater. "Two ongoing trials investigating ribociclib and one investigating abemaciclib as selective inhibitors of CDK4 and CDK6 are investigating the role of CDK inhibitors in treating meningiomas (NCT02933736, NCT03220646, NCT02523014)." (PMID 36672431, 2023). "Our results demonstrate hyperphosphorylation of RB1 Ser780 and increased CCND1, CDK4, and CDK6 expression in high-grade meningiomas and after AKAP12 knockdown." (PMID 29391485, 2018). "Furthermore, dysregulation of p16, CDK6, and pRB protein have all been associated with recurrence in atypical meningiomas and homozygous deletions of the CDKN2A/B gene has also been associated with early meningioma recurrence." (PMID 35936751, 2022). "Although only in single studies, KPNA2, CDK6, Cox-2, MCM7 and PCNA are proposed as additional markers with high expression that are related with poor prognosis of meningioma patients." (PMID 38758750, 2024). "In our study, fibroblastic meningioma was detected with increasing expression of CCND1, CDK6, and E2F3, and decreasing expression of CDKs inhibitors including CDKN1A, CDKN2A, and CDKN2B, suggesting a role of cell cycle deregulation in the tumorigenesis of fibroblastic meningioma." (PMID 23285163, 2012).
metastatic tumors (6 papers, 2014 to 2025). "Cox proportional hazard regression analysis of PFS according to the signatures of CDK6, p-CDK2 and cyclin E1 and clinicopathological parameters of the metastatic disease showed that the combined biomarkers signature was an independent prognostic factor of PFS in both tested cohorts." (PMID 36153348, 2022).
squamous cell carcinoma (6 papers, 2012 to 2021). A carcinoma arising from squamous epithelial cells. "The role of CDK6 in both proliferation and invasiveness has been already reported in squamous carcinoma cells." (PMID 33462405, 2021). "Thus, it was implied that crosstalk between YAP1 and CDK6 seems to play a pivotal role in conferring radiation resistance and targeting both YAP1 and CDK6 could be a useful therapeutic strategy to treat both esophageal adenocarcinoma and squamous cell carcinoma." (PMID 33665161, 2020).
triple-negative breast carcinoma (6 papers, 2020 to 2025). An invasive breast carcinoma which is negative for expression of estrogen receptor (ER), progesterone receptor (PR), and human epidermal growth factor receptor 2 (HER2). "IGF2BP2 promotes cyclin-dependent kinase 6 (CDK6) translation via eIF4A1 recruitment, driving cell cycle progression and G1/S phase transition in triple-negative breast cancer." (PMID 40986143, 2025). "For example, in triple-negative breast cancer (TNBC), IGF2BP2 enhances cell proliferation and facilitates the G1/S phase transition by directly regulating CDK6 in an m6A-dependent manner and recruiting EIF4A1 to promote CDK6 translation output." (PMID 39596216, 2024). "Knockdown of ZNF703 in triple-negative breast cancer cells was shown to inhibit the expression of cyclin D1, CDK4, CDK6, and E2F1 and upregulation of Rb1." (PMID 37686244, 2023). "Studies on MDA-MB-231, a triple negative breast cancer cell line, showed that CDK4 is degraded more efficiently and PROTAC containing palbociclib (22a) is more potent (DC50 CDK4 = 12.9 nM, DC50 CDK6 = 34.1 nM) than 22b (DC50 CDK4 = 97 nM, DC50 CDK6 = 300 nM)." (PMID 33803309, 2021).
Alzheimer disease (5 papers, 2021 to 2025). A progressive, neurodegenerative disease characterized by loss of function and death of nerve cells in several areas of the brain leading to loss of cognitive function such as memory and language. "YAP has been shown to prevent premature senescence of astrocytes and cognitive decline in Alzheimer’s disease by regulating CDK6 signaling." (PMID 38001078, 2023). "Even in mouse models of Alzheimer's disease (AD), YAP acts as an inhibitor to partially postpone the senescence of astrocytes through cyclin-dependent kinase 6 (CDK6) signaling to improve cognitive function." (PMID 39503968, 2025).
chordoma (5 papers, 2020 to 2025). Chordomas are rare malignant tumors arising from embryonic remnants of the notochord in axial skeleton. "Genes previously implicated in chordoma biology, including CDK6, SOX9, and EGFR, were also recovered." (PMID 37024492, 2023). "Chordoma’s apparent CDK6 dependence and potential ferroptosis susceptibility raises intriguing and unexpected parallels with clear-cell carcinomas." (PMID 36387127, 2022). "Several chordoma dependency genes identified in the primary screens, including PTPN11, EGFR, and CDK6, encode proteins that are currently targetable with small-molecule inhibitors." (PMID 37024492, 2023). "For example, U-CH2 and MUG-Chor1 chordoma cell lines each show biallelic loss of CDKN2A, as well as highly selective dependence on CDK6." (PMID 37024492, 2023). "From a gene expression perspective, CDK4 and CDK6 mRNAs have been detected in all eight chordoma cell lines that were interrogated: U-CH1, U-CH2, U-CH3, U-CH6, U-CH7, U-CH10, U-CH11, and U-CH1243." (PMID 32737414, 2020). "Interestingly, expression of CDK6 – an apparent dependency in both chordoma and ccRCC – appears to be regulated by brachyury." (PMID 36387127, 2022). "CDK6 may therefore be crucial for maintaining redox homeostasis in chordoma to safeguard against ferroptosis, providing rationale for evaluation of CDK4/6 inhibitors in combination with ferroptosis inducers." (PMID 36387127, 2022). "Genes were selected to represent both those functionally connected to other chordoma dependency genes (PTPN11, FANCM, ADAR, PRKRA, SOX9, SRRM2, SLC2A1, and SLC7A5), as well as those with putatively unique effects (LUC7L2 and CDK6)." (PMID 37024492, 2023). "Other CDK inhibitors like palbociclib (CDK4 and CDK6) were also able to reduce chordoma cell line proliferation but did not result in any significant reduction in brachyury." (PMID 38786326, 2024). "Several candidate genes, including OTUD5, CDK6, LUC7L2, IER3IP1, and HEATR3, were not linked to other chordoma dependency genes following either of these two approaches." (PMID 37024492, 2023). "For example, CDK6 – but not CDK4 – appears to be a genetic essentiality in some chordoma cell lines." (PMID 36387127, 2022). "A body of such molecular, preclinical, and clinical evidence of interest to chordoma oncogenesis has begun to emerge for several kinases: Epidermal Growth Factor Receptor (EGFR), Cyclin-dependent kinase 4 (CDK4), Cyclin-dependent kinase 6 (CDK6) and the mammalian target of rapamycin (mTOR)." (PMID 32737414, 2020).
diabetes (5 papers, 2014 to 2025). "Contrastingly, mRNAs levels of cell cycle promoters including cyclin-dependent kinase (CDK) 4, (CDK4), CDK6 and Cyclin D1 showed marked reduction during the course of diabetes." (PMID 30720765, 2019). "This is thought to be due to the CDKN2A and CDKN2B genes in this genomic region inhibiting CDK4 and CDK6, which has been demonstrated to influence β cell proliferation and mass, eventually leading to diabetes." (PMID 25430018, 2014).
diffuse large B-cell lymphoma (5 papers, 2013 to 2025). "Noteworthy findings included the high activity of CDK6 substrates in the Pfeiffer cell line, a diffuse large B-cell lymphoma line, aligning with reports that CDK4/6 inhibitors are effective against aggressive B-cell lymphomas." (PMID 41035678, 2025). "Prognostic analysis reveals that the expression levels of CDK6, BCL2, and DNMT3B are closely associated with the prognosis in human diffuse large B-cell lymphoma." (PMID 39864628, 2025). "Additionally, we investigated 33 diffuse large B cell lymphoma (DLBCL) cases for the correlation of CDK6 expression and blood vessel density." (PMID 23948297, 2013).
esophageal squamous cell carcinoma (5 papers, 2018 to 2021). Esophageal squamous cell carcinoma (ESCC) is a type of esophageal carcinoma (EC) that can affect any part of the esophagus, but is usually located in the upper or middle third. "On the other hand, the regulatory role and pathological significance of the LINE-1 methylation pattern is indicated by the fact, that in patients with hypomethylated LINE-1 and with cyclin-dependent kinase-6 (CDK6) amplified esophageal squamous cell carcinoma the expression of P21 decreased." (PMID 33878138, 2021). "lncRNA Xist involves esophageal squamous cell carcinoma development via regulation of miR-101/EZH2 axis, and facilitates esophageal squamous cell carcinoma proliferation, apoptosis, migration, and invasion via regulation miR-494/CDK6 axis and activation of JAK2/STAT3 signal pathway." (PMID 34178980, 2021).
gallbladder cancer (5 papers, 2015 to 2025). "Neferine inhibits the proliferation of human gallbladder cancer cells through the CDK4/CDK6/CyclinD1 pathway." (PMID 40138292, 2025). "In a murine xenograft model, locally injected microRNA-34a-5p mimics significantly inhibited gallbladder cancer progression and downregulated CDK6 expression." (PMID 38596294, 2024). "CircHIPK3 was found to facilitate gallbladder cancer cell proliferation via inhibiting the activity of miR-124 and enhancing rho-associated protein kinase 1(ROCK1) and cyclin dependent kinase 6 (CDK6) expression." (PMID 36606192, 2022). "In three different human gallbladder cancer cell lines, forced microRNA-34a-5p expression inhibited cell proliferation and induced cell-cycle arrest at the G1 phase by suppressing direct target (CDK6) expression." (PMID 38596294, 2024).